SNORD63B (small nucleolar RNA, C/D box 63B)
Gene: Small nucleolar RNA gene on chromosome 5 (138,558,970 to 138,559,039, reverse strand). Ensembl gene ENSG00000222937.
Gene Ontology:
Biological process: RNA processing
Cellular component: nucleolus
Homologues: Orthologues: chimpanzee SNORD63 (99% identical), macaque SNORD63 (93% identical), dog SNORD63 (83% identical), rat LOC120098355 (83% identical), mouse Gm22200 (74% identical), zebrafish SNORD63 (46% identical). Paralogues in human: SNORD63 (67% identical), SNORD63 (53% identical), SNORD63 (51% identical).